DND1 (DND microRNA-mediated repression inhibitor 1)
Description:
RNA-binding factor that positively regulates gene expression by prohibiting miRNA-mediated gene suppression. Relieves miRNA repression in germline cells (By similarity). Prohibits the function of several miRNAs by blocking the accessibility of target mRNAs. Sequence-specific RNA-binding factor that binds specifically to U-rich regions (URRs) in the 3' untranslated region (3'-UTR) of several mRNAs. Does not bind to miRNAs. May play a role during primordial germ cell (PGC) survival (By similarity). However, does not seem to be essential for PGC migration (By similarity).
Synonyms: RBMS4; MGC34750
Tractability: PROTAC: ubiquitination databases record sites on it.
Gene: Protein-coding gene on chromosome 5 (140,670,794 to 140,673,576, reverse strand). Ensembl gene ENSG00000256453.
Subcellular location: Nucleus; Cytoplasm
Subcellular location (Human Protein Atlas): Nucleoplasm; Cytosol; Focal adhesion sites
Gene Ontology:
Molecular function: miRNA binding; mRNA 3'-UTR binding; protein binding; mRNA binding; nucleic acid binding; RNA binding
Biological process: 3'-UTR-mediated mRNA destabilization; negative regulation of miRNA-mediated gene silencing; mRNA stabilization; germ cell development; spermatogenesis
Cellular component: cytoplasm; cytosol; nucleoplasm; nucleus
Genetic constraint (gnomAD): Loss-of-function variants: 8 observed, 22.75 expected, observed/expected ratio (o/e) 0.35, 90% interval 0.2 to 0.63. The upper end of that interval is the gene's LOEUF score, 0.63, which puts it in group 2 of 6, group 1 being the genes least tolerant of losing a copy. Missense variants: 358 observed, 363.57 expected, observed/expected ratio (o/e) 0.98, 90% interval 0.9 to 1.08. Synonymous variants: 178 observed, 146.86 expected, observed/expected ratio (o/e) 1.21, 90% interval 1.07 to 1.37.
Homologues: Orthologues: chimpanzee DND1 (99% identical), macaque DND1 (94% identical), pig DND1 (92% identical), dog DND1 (90% identical), guinea pig DND1 (90% identical), mouse Dnd1 (86% identical), rat Dnd1 (86% identical), rabbit DND1 (83% identical), tropical clawed frog dnd1 (47% identical), zebrafish dnd1 (36% identical). Paralogues in human: A1CF (33% identical), RBM46 (31% identical), RBM47 (30% identical), RBM19 (15% identical), RBMX (15% identical), RBM39 (15% identical), RBMXL2 (15% identical), RBMXL1 (14% identical), NUCLEOLIN (14% identical), HNRNPA3 (14% identical), HNRNPA1 (12% identical), MSI1 (12% identical), and 24 more.
Diseases named in the same sentence as DND1 in open-access papers:
DND1 is named in the same sentence as 40 diseases in open-access papers, as found by Europe PMC text mining. Sharing a sentence is not in itself a finding about the gene and the disease. The quoted sentences say what the papers report.
teratoma (15 papers, 2011 to 2023). A non-seminomatous germ cell tumor characterized by the presence of various tissues which correspond to the different germinal layers (endoderm, mesoderm, and ectoderm). "Loss of Dnd1 function results in germ cell differentiation to teratomas in some inbred strains of mice or to somatic fates in zebrafish." (PMID 36857387, 2023). "It was suggested that the effect of the missense mutation in MC4R on teratoma formation was promoted by abnormal germ cell formation by the mutation in DND1." (PMID 33568756, 2021). "In the 129 strain, the Dnd1-Δ allele significantly increased teratoma occurrence in male mice from a baseline of 4.2% to 28.8% in Dnd1+/Δ heterozygotes and 92.6% in Dnd1Δ/Δ homozygotes, which are ratios similar to those for Ter mutant mice." (PMID 32339196, 2020). "Mutation of the dead-end 1 (Dnd1) gene, which encodes an RNA-binding protein, drastically enhances teratoma formation in the 129/Sv mouse strain." (PMID 29378702, 2018). "The immortalized tumor derived rat fibroblast TRF-O3 cells isolated from a Dnd1-deficient teratoma were identified as optimal feeder cells supporting stemness and proliferation of rat ESC." (PMID 25332888, 2014). "Previously genetic alterations in germ cells, including the ter mutation in the Dnd1 gene, loss of Dmrt1, or loss of Pten produced a high incidence of TGCTs (particularly teratomas) in mice." (PMID 22348147, 2012). "The close similarities found between Dnd1 mutant mouse and rat in the mutation and the phenotype make it probable that a functional inactivation of Dnd1 causes germ cell loss and teratomas in the ter rat." (PMID 22655094, 2012). "However, the Ter mutation in the Dnd1 gene on the 129 genetic background strikingly results in spontaneous teratoma formation at E16.5." (PMID 37900284, 2023). "Several studies demonstrated that a number of molecules are involved in teratoma formation caused by deficiency in the Dnd1 gene; moreover, enhancement of the cell cycle and suppression of apoptosis are likely key events for the conversion of PGCs into teratoma." (PMID 34205983, 2021). "Dnd1 mutation is present in 129 strain and greatly enhances teratoma formation on its own." (PMID 31752312, 2019). "Taken together, the results suggested that the downregulation of Ccnd1 caused by Dnd1-mediated expression of Ezh2 may be crucial for the suppression of teratoma development in germ cells." (PMID 29378702, 2018). "Mice deficient for Pten and Dnd1 also display increased teratoma formation." (PMID 23967156, 2013). "Thus, a loss-of-function mutation in DND1 is essential for teratoma formation." (PMID 33568756, 2021). "However, the following are unclear: (a) whether DND1 works with NANOS2 or NANOS3 to regulate teratoma incidence, and (b) whether Ter simply causes Dnd1 loss or produces a short mutant DND1 protein." (PMID 32339196, 2020). "This is a possible mechanism to explain the left-bias of teratoma development in 129/SvJ Dnd1+/− mice." (PMID 37180974, 2023). "The regulation of multiple epigenetic enzymes by DND1 suggests that one reason that Dnd1Ter/Ter mutant germ cells tend to give rise to teratomas is a failure to epigenetically silence somatic gene expression." (PMID 36857387, 2023). "Then, it was revealed that the Ter gene product DND1 is essential for germ cell formation and that other genes are also necessary for the onset of teratomas." (PMID 33568756, 2021). "Matsui and colleagues reported the successful isolation of a new type of pluripotent stem cells, which can be differentiated to all three germ layers from the nascent teratoma of Dead end 1 (Dnd1) mutant." (PMID 31752312, 2019). "We next attempted to elucidate the Dnd1-related molecular pathway that regulates the conversion of embryonic testicular germ cells into teratoma-forming cells." (PMID 29378702, 2018).
teratoma (continued). "Our results showed a molecular linkage between Dnd1, its target, enhancer of zeste homolog 2 (Ezh2), as well as a target of Ezh2, cyclin D1 (Ccnd1), in the conversion of embryonic germ cells into teratoma-forming cells." (PMID 29378702, 2018). "Our results from the present study suggest that Ccnd1 is controlled by Dnd1 via epigenetic regulation, and it is involved in teratoma formation." (PMID 29378702, 2018). "In a previous study, teratoma-forming Dnd1-mutant germ cells in the 129Sv background were initially identified as morphologically abnormal cells showing a high nucleo-cytoplasmic ratio at as early as E14." (PMID 29378702, 2018). "The amount of Dnd1 cDNA found in the teratomas was in the same range as wild type testes, while comparatively low levels were exhibited in the degenerated testis (right)." (PMID 22655094, 2012). "While the mouse Dnd1 was characterized as a modifier gene that modulates teratoma formation in males, our data suggests that rat Dnd1 acts as a tumor suppressor gene in both genders of the WKY/Ztm strain." (PMID 22655094, 2012). "Interestingly, the left-bias in tumor incidence was observed in wild type mice (Dnd1+/+ littermates) where the total tumor incidence was ∼2%, and in 80% of these cases teratomas developed in the left testis." (PMID 37180974, 2023). "Mutation in Dnd1 resulted in downregulation of Ezh2, a core member of polycomb protein complex 2 (Prc2), responsible for catalyzing H3K27 tri-methylation in PGCs forming teratoma." (PMID 34205983, 2021). "In the current study, we newly established a conventional Dnd1-knockout mouse line and found that these mice showed phenotypes similar to those of Ter mutant mice in spermatogenesis, oogenesis, and teratoma incidence, with a slight difference in spermiogenesis." (PMID 32339196, 2020). "In addition to these genetic interactions, given that both NANOS2 and NANOS3 associate with DND1, it is highly plausible that both DND1-NANOS2 and DND1-NANOS3 complexes regulate teratoma incidence in male embryonic germ cells." (PMID 32339196, 2020). "Dnd1-induced downregulation of the expression of CDK inhibitors in embryonic germ cells may also be involved in inhibiting teratoma formation." (PMID 29378702, 2018). "Therefore, it is feasible that the distribution of Dnd1 in a teratoma depends on the tissue predominant in the respective sample." (PMID 22655094, 2012). "Furthermore, the Dnd1 expression of three ter/ter animals with unilateral TGCT was measured in both the teratoma and the contralateral degenerated testis." (PMID 22655094, 2012). "For example mice with mutations in Dnd1 readily form teratomas in 129/SvJ mice, but do not normally form similar tumours in mice of the C57Bl/6J, LTXBJ or C3H/HeJ backgrounds as the germ cells die." (PMID 21674058, 2011). "We then examined whether the timing of Dnd1 loss in PGCs contributed to the onset of teratoma because Dnd1-cKO mice did not develop STTs when tamoxifen was injected at E13.516." (PMID 37076592, 2023). "Interestingly, Dnd1-mediated epigenetic control of teratoma formation has been recently reported." (PMID 34205983, 2021). "However, Dnd1 null mice of a mixed 129/SvJ-C57Bl/6 Bax null background form teratomas with high frequency indicating that germ cell death is important in preventing teratomas." (PMID 21674058, 2011). "In addition, it was recently reported that a targeted deletion of Dnd1 did not affect teratoma incidence in the 129S1/SvImJ genetic background; rather, it induced embryonic lethality before E 3.5." (PMID 32339196, 2020). "In addition, the decreased expression of Dnd1 in cultured PGCs in the condition for PGC reprogramming was consistent with its negative influence on the development of teratoma-forming cells." (PMID 29378702, 2018).
testicular germ cell tumor (11 papers, 2008 to 2025). A germ cell tumor arising from the testis. "Chromosomal deletions in human 5q have been identified in germ-cell tumor tissues and germ-cell tumor cell lines, and Dnd1 mutations have also been found in TGCTs." (PMID 25405725, 2015). "Certain mutations in the Deadend1 (Dnd1) gene are the most potent modifiers of testicular germ cell tumor (TGCT) susceptibility in mice and rats." (PMID 23773267, 2013). "Inactivation of the Dnd1 gene results in sterility in vertebrates as well as causes development of testicular germ cell tumors in mice." (PMID 21851623, 2011). "The inactivating mutation in the Dnd1 gene in Ter mice causes either sterility or testicular germ cell tumor development." (PMID 18509452, 2008). "In 129 strain mice, inactivation of Dnd1, as in the 129-Ter mouse strain, causes loss of germ cells and in addition, development of testicular germ cell tumors." (PMID 18509452, 2008). "A mutation in Dnd1 causes germ cell loss and testicular germ cell tumors in mice." (PMID 29222434, 2017). "In addition, a disease associated nucleotide polymorphism in the highly conserved RRM of DND1 was detected in a human patient with germ cell tumor." (PMID 21851623, 2011). "First cloned from Ter mutant mouse, it was found that a point mutation occurring in Dnd1 gene generates an early termination codon and is responsible for the testicular germ cell tumor (TGCT) phenotype resembling that of Ter mutation in human." (PMID 26839690, 2016). "DND1 function is required for the survival of primordial germ cells and SSCs and, in some genetic backgrounds, to prevent the development of testicular germ cell tumors." (PMID 40814964, 2025). "It provided evidence that DND1 maintains germ cell viability and inhibits the formation of germ cell tumors by counteracting microRNA-mediated silencing of mRNAs." (PMID 34721738, 2021). "Although DND1 was initially identified for its role in germ cells and germ cell tumors, emerging evidence indicates a wider role for DND1 in mammalian tissues, especially in cancers." (PMID 23890083, 2013). "When Dnd1 is functionally inactivated, as in the Ter mutant mouse strain, this results in death of germ cells, sterility, and in some cases development of testicular germ cell tumors." (PMID 23890083, 2013). "Germ cell tumor development in 129-Ter/Ter (Dnd1-/-) mice is also initiated during embryonic stages." (PMID 18509452, 2008). "DND1 is found in the fetal testis during the critical period when testicular germ cell tumors (TGCTs) are hypothesized to develop in mice." (PMID 25405725, 2015). "In 129 inbred mice, a point mutation in Dnd1 introduced a stop codon, which resulted in truncated Dnd1, which may give rise to PGC deficiency, testicular germ cell tumor development and partial embryonic lethality." (PMID 25405725, 2015). "In addition, when inactivation of Dnd1 occurs in 129 strain mouse background, these mice have a very high incidence of testicular germ cell tumors." (PMID 21851623, 2011). "Understanding the role of DND1-APOBEC3 interaction will not only shed light on the development of testicular germ cell tumors in mice and humans but may also have profound implications for our understanding of the mechanism of how cancers in general originate in humans." (PMID 18509452, 2008). "One possibility is that absence of DND1 may cause deficiency of tumor suppressor proteins and this may cause germ cell tumor development." (PMID 18509452, 2008). "The interaction of DND1 and APOBEC3 could be one mechanism for maintaining viability of germ cells and for preventing germ cell tumor development." (PMID 18509452, 2008). "Moreover, lack of Dnd1 at these embryonic stages also results in initiation of germ cell tumors in the 129 strain male." (PMID 18509452, 2008).
Infertility (7 papers, 2012 to 2023). "Disruption of the dnd1 gene results in the development of infertile males in adults in D. rerio and causes deficiency of primordial germ cells and infertility in mice." (PMID 37566603, 2023). "To identify the cause of infertility in 129 Dnd1+/Δ male mice, we compared the ratios of testis weight per body weight of 4-week-old wild-type and Dnd1+/Δ male mice with those of 12-week-old male mice in each of the three strains." (PMID 32339196, 2020). "We traced the ter mutation in the WKY/Ztm rat strain to a point mutation in the Dnd1 gene and observed teratocarcinomas and infertility in all homozygous rats of both genders." (PMID 22655094, 2012). "We detected a congenital, recessive point mutation referred to as ter in the rat Dnd1 gene on chromosome 18p11 that induces teratocarcinogenesis and infertility in all homozygous animals of both genders." (PMID 22655094, 2012). "In 2003, infertility control was achieved by the knockdown of the dnd1 gene’s expression using a morpholino, but performing a microinjection of one-cell fertilized eggs is an operation that is too technically complex to be applied in the industry." (PMID 36713075, 2023). "In our study, CRISPR/Cas9 technology, which needs only prepare a single guide RNA and Cas9 mRNA to induce dsDNA break for genome editing, was used to knockout dnd1 gene for complete infertility control of transgenic fish." (PMID 36713075, 2023). "In the present study, we first reported that missense mutation in DND1, an RNA-binding protein that plays an essential role in primordial germ cells (PGCs) survival, caused NOA in patients with infertility from a Pakistani family." (PMID 36246621, 2022). "The result above shows that the infertility control technology could actually be applied to prevent the gene flow of transgene because the mutant dnd1 individuals lost germ cells and the ability to fertilize eggs." (PMID 36713075, 2023). "As dnd1 is a critical gene that has been proven to be important in the migration and cell fate stability of PGCs, several researchers have focused on dnd1 to perform gene disruption to explore the possibility of infertility control." (PMID 36713075, 2023). "Therefore, CRISPR/Cas9 technology had been applied in genome editing of several fish species such as Atlantic salmon, medaka, sterlet, and rainbow trout to target dnd1 to achieve infertility." (PMID 36713075, 2023). "Furthermore, we focused on the development of gonads in sexually mature individuals to discover whether dnd1 knockout led to infertility." (PMID 36713075, 2023). "We established dnd1-knockout zebrafish using CRISPR/Cas9 gene editing technology and achieved complete infertility in homozygotic individuals of transgenic cyan fluorescent zebrafish." (PMID 36713075, 2023). "Although dnd1 knockout in zebrafish was achieved by ZFNs, CRISPR/Cas9 technology was still not applied in dnd1 knockout of zebrafish, especially in new application of infertility control of transgenic fluorescent zebrafish as a model of fluorescent ornamental fish." (PMID 36713075, 2023). "This technology applied in model species, such as zebrafish, could help us to explore whether the lack of dnd1 generated by CRISPR/Cas9 could allow complete infertility to be achieved and a complete analytical procedure to be established in a shorter period of time." (PMID 36713075, 2023).